BRD2 (bromodomain containing 2)
Diseases named in the same sentence as BRD2 in open-access papers (continued):
Sharing a sentence is not in itself a finding about the gene and the disease.
Cachexia (1 paper, 2017). Severe weight loss, wasting of muscle, loss of appetite, and general debility related to a chronic disease. "BRD2 associates with MAFbx/Atrogin1 and GABARAPL1 promoters during cachexia, and this association is abrogated by (+)-JQ1 treatment." (PMID 29167426, 2017). "At the onset of cancer cachexia, direct BRD4 and BRD2 recruitment at muscle catabolic genes is likely favored by local increase in histone acetylation, in concert with sustained engagement of transcription factors (e.g., FoxO3) and co-factors at chromatin regulatory regions." (PMID 29167426, 2017). "Because of BRD2 overlapping regulation in several subsets of BRD4 targets, we investigated BRD2 ability to engage MAFbx/Atrogin1, MuRF1, and GABARAPL1 loci, during cachexia." (PMID 29167426, 2017). "However, BRD2 was not recruited at MuRF1 promoter and enhancer regions, suggesting that BRD4 is the principal BET protein-regulating MuRF1 transcription, during cachexia." (PMID 29167426, 2017).
cardiac hypertrophy (1 paper, 2022). "In view of this, the present study attempted to determine the regulatory effect of BRD2 in pathological cardiac hypertrophy, and to explore the possible underlying mechanisms." (PMID 35694272, 2022). "BRD2 was remarkably elevated at the transcriptional level in parallel with BRD4, suggesting that BRD2 is probably associated with the pathological progression of cardiac hypertrophy." (PMID 35694272, 2022). "The present study identified BRD2 as a novel regulator in cardiac hypertrophy, with a distinct mechanism from BRD4." (PMID 35694272, 2022). "Consistent with results of OCR and ATP production, these findings confirm that BRD2 facilitates cardiac hypertrophy via regulating energy metabolism." (PMID 35694272, 2022). "Results of mitochondrial oxygen consumption rate (OCR) and ATP production measurement demonstrated that BRD2 augmented cardiac metabolism during cardiac hypertrophy." (PMID 35694272, 2022). "We further evaluated the potential effect of BRD2 knockdown in rats with pathological cardiac hypertrophy." (PMID 35694272, 2022). "BRD2 expression was elevated in cardiac hypertrophy induced by β-adrenergic agonist isoprenaline (ISO) in vivo and in vitro." (PMID 35694272, 2022). "In conclusion, the present study revealed that BRD2 could facilitate cardiac hypertrophy through upregulating TCA cycle genes." (PMID 35694272, 2022). "Strategies targeting inhibition of BRD2 might suggest therapeutic potential for pathological cardiac hypertrophy and heart failure." (PMID 35694272, 2022). "In conclusion, the present study identified BRD2 as a novel regulator of pathological cardiac hypertrophy, which could facilitate cardiac hypertrophy through upregulating gene expression of cardiac metabolic enzymes in particular those in TCA cycle." (PMID 35694272, 2022). "Repression or inhibition of BRD2 might help to ameliorate these processes and prevent the development of cardiac hypertrophy." (PMID 35694272, 2022). "Therefore, these in vivo findings confirm that BRD2 ablation confers protection against pathological cardiac hypertrophy." (PMID 35694272, 2022). "Therefore, the present findings that BRD2 regulates cardiac metabolism might elucidate a unique mechanism of BET family in the regulation of cardiac hypertrophy, in addition to that of BRD4 with the function of long CTD." (PMID 35694272, 2022). "It remains unclear how BRD2 regulates the expression of metabolic genes during cardiac hypertrophy." (PMID 35694272, 2022). "Notably, BRD2 shares close similarity in structure and physiological role with BRD4, which is well-accepted to be a nodal regulator of cardiac hypertrophy." (PMID 35694272, 2022). "To explore the possible mechanisms of BRD2 in regulation of cardiac hypertrophy, we conducted RNA sequencing analysis to investigate the transcriptome changes in NRCMs with BRD2 overexpression or silencing, in the presence or absence of ISO." (PMID 35694272, 2022). "Thus, the lack of long CTD in BRD2 might exclude the possibility that BRD2 regulates cardiac hypertrophy in a similar mechanism as BRD4." (PMID 35694272, 2022). "However, the present data did not allow to speculate whether the regulatory mechanism of BRD2 and BRD4 in cardiac hypertrophy are connected or not." (PMID 35694272, 2022). "The present results that BRD2 exerted pro-hypertrophic effects in cardiomyocytes, apart from the previously reported BRD4, might help to explain the promising effect of pan-BETi in treatment of pathological cardiac hypertrophy, rather than specific inhibitor of a single BET member." (PMID 35694272, 2022).
celiac disease (1 paper, 2016). An autoimmune genetic disorder with an unknown pattern of inheritance that primarily affects the digestive tract. "Notably, we did not confirm any association of BRD2 rs1049526 with 458, 133, and 542 patients with primary biliary cirrhosis, primary sclerosing cholangitis, and celiac disease, respectively (data not shown)." (PMID 28008999, 2016).
endometrioid ovarian cancer (1 paper, 2022). "Nevertheless, BRD2 mRNA high expression of endometrioid ovarian cancer did not display any association with OS, HR = 2.96 (0.33 - 26.54), P=0.31." (PMID 35371325, 2022).
Ewing sarcoma (1 paper, 2016). A small round cell tumor that lacks morphologic, immunohistochemical, and electron microscopic evidence of neuroectodermal differentiation. "To directly assess the relevance of targeting BET bromodomain proteins signaling in Ewing Sarcoma disease, we first evaluated the messenger RNA expression level of BRD2, BRD3 and BRD4 in ten human Ewing Sarcoma cell lines." (PMID 27006472, 2016).
generalized seizures (1 paper, 2011). "The decrease in the flurothyl-induced, primarily generalized seizure threshold and the presence of spontaneous primary generalized seizures in Brd2+/− mice suggested that there might be changes in the generalized seizure control system, which includes the SNR, and significant GABA involvement." (PMID 21887291, 2011).
hyperglycaemia (1 paper, 2020). "Interestingly, BRD2, which contained a DMR associated with both 1-h and 2-h PG, is known to interact with ZMYND8 and was previously reported by Houde and colleagues to be associated with maternal hyperglycaemia." (PMID 33151971, 2020).
hyperuricemia (1 paper, 2021). An abnormally high level of uric acid. "Thus, hyperuricemia mainly induces expression of Brd2 and Brd4, which was sensitive to I-BET151 inhibition." (PMID 33664670, 2021). "In response to hyperuricemia, renal expression of Brd2 was induced, Brd4 upregulated, but Brd3 expression was not altered; administration of I-BET151 abolished expression of Brd2 and Brd4, but did not affect Brd3 expression in the kidney of HN." (PMID 33664670, 2021).
kidney damage (1 paper, 2020). "Oxidative stress is a major contributor to kidney damage, and increased levels of BRD2 induce oxidative stress in human cells." (PMID 32559200, 2020).
liver fibrosis (1 paper, 2025). "Furthermore, Western blot analysis of liver tissues revealed elevated expression of BRD4, but not BRD2 and BRD3 in the CDAA-HFD group, again suggesting BRD4 as the major protein that mediates liver fibrosis." (PMID 40756370, 2025).
lung adenocarcinoma (1 paper, 2025). A carcinoma that arises from the lung and is characterized by the presence of malignant glandular epithelial cells. "Our observation in a dataset from 111 lung adenocarcinoma (LUAD) patients indicates that levels of BRD2 positively correlate with different stages of cancers." (PMID 40652527, 2025). "We sought to evaluate the expression pattern of BRD2 by using the Clinical Proteomic Tumor Analysis Consortium (CPTAC) for the lung adenocarcinoma dataset." (PMID 40652527, 2025). "We discovered that in a cohort of primary lung adenocarcinoma (LUAD) patients (n = 111), BRD2 expression was higher than in healthy subjects (P < 0.0001)." (PMID 40652527, 2025).
lymphocytic leukemias (1 paper, 2018). "However, similar to our results, it was previously reported that JQ1 or BRD2 downregulation diminishes STAT5 function through phosphorylation-independent mechanisms in lymphocytic leukemias." (PMID 30733722, 2018).
mantle cell lymphoma (1 paper, 2019). Mantle cell lymphoma is a rare form of malignant non-Hodgkin lymphoma affecting B lymphocytes in the lymph nodes in a region called the ``mantle zone''. "The treatment of mantle cell lymphoma cells with two different BET-PROTACs (ARV-771 and ARV-825), targeting BRD4 or BRD2/3/4, respectively, showed more potent apoptotic effect compared to iBET OTX015 (MK-8628), an iBET that selectively blocks BRD2/3/4." (PMID 31780938, 2019).
myelofibrosis (1 paper, 2024). A partial or complete replacement of the bone marrow stroma by fibrous tissue. "This compound is an experimental myelofibrosis and cancer drug (clinicaltrials.gov, NCT04454658, accessed July 21, 2023) that acts as an inhibitor of BET bromodomain proteins, specifically BD2 domain of BRD2, BRD3 and BRD4." (PMID 38526670, 2024).
nut midline carcinoma (1 paper, 2015). A rare, highly aggressive and lethal carcinoma that affects children and young adults. "It has also been demonstrated that the BET inhibitors I-BET151 and I-BET762 (currently under clinical investigation in NUT-midline carcinoma) exert their biologic activity via BRD2 decrease." (PMID 25989842, 2015).
oropharynx cancer (1 paper, 2024). A primary or metastatic malignant neoplasm that affects the oropharynx. "The phenotype scan results revealed associations between BRD2 and traits such as lymphocyte count, oropharynx cancer, and nuclear pore membrane glycoprotein 210-like levels." (PMID 38903171, 2024).
osteoporosis (1 paper, 2016). A condition of reduced bone mass, with decreased cortical thickness and a decrease in the number and size of the trabeculae of cancellous bone (but normal chemical composition), resulting in increased fracture incidence. "Recently, we showed that NMP acts as a low affinity bromodomain inhibitor for BRD2, BRD3, BRD4, and BRDT and has potential for osteoporosis treatment." (PMID 27110299, 2016).
pancreatic cancer (1 paper, 2026). "At the chromatin level, BRD2 and BRD4 ChIP-seq analysis of pancreatic cancer cells showed consistent BRD4 loss from chromatin after JQ1 treatment, while BRD2 displacement differed by sensitivity." (PMID 42069518, 2026).
pancreatic NETs (1 paper, 2020). "In our study, we demonstrate that AtT20 cells express the BET family members Brd2, Brd3 and Brd4, with Brd2 being the most abundant, which is similar to data reported for MEN1-associated mouse pancreatic NETs and human pancreatic and bronchial NET cell lines." (PMID 31935194, 2020).
pulmonary diseases (1 paper, 2023). "Consequently, the documented experimental, and natural infectious of OvGHV2 associated pulmonary diseases, as well as the results herein described, corroborate with the hypothesis that OvGHV2 should be considered as a potential pathogenic agent of BRD2." (PMID 37024495, 2023).
sarcoma (1 paper, 2024). A usually aggressive malignant neoplasm of the soft tissue or bone. "Accordingly, we utilized GEPIA to conduct survival analysis and demonstrated that BRD2 expression levels were significantly associated with the OS of sarcoma patients." (PMID 39273015, 2024). "Our survival analysis revealed a significant difference in OS between the high (n = 131) and low expression (n = 131) groups of the BRD2 gene in sarcoma patients." (PMID 39273015, 2024).
Stroke (1 paper, 2025). Sudden impairment of blood flow to a part of the brain due to occlusion or rupture of an artery to the brain. "Our results showed that ECH1, MAPK14, and BRD2 were significantly correlated with stroke, and no pleiotropy or heterogeneity was detected (P < 0.05)." (PMID 40918984, 2025).
cancer (56 papers, 2013 to 2026). A tumor composed of atypical neoplastic, often pleomorphic cells that invade other tissues. "The elevated expression of BRD2/BRD3/BRD4/YAP1 is a risk factor from the Cox cross-pan-cancer dataset proportional hazards model in a variety of tumors, including SKCM, besides, there was an association between BRD4 and YAP1." (PMID 38169595, 2024). "The mammalian bromodomain and extra-terminal domain (BET) family of proteins consists of four conserved members (Brd2, Brd3, Brd4, and Brdt) that regulate numerous cancer-related and immunity-associated genes." (PMID 37049806, 2023). "Whereas decreased Brd2 expression is associated with longevity-promoting processes, increased Brd2 expression can promote cancer in murine hematopoietic cells and in B-lymphocytes." (PMID 32559200, 2020). "We identified BRD2 upregulation as a conserved response to BET inhibition across multiple cancer types and hypothesized that BRD2 compensates for BRD4 loss, sustaining essential transcriptional programs upon treatment." (PMID 42069518, 2026). "Because cancer is a major cause of age-related morbidity and mortality, we hypothesize that Brd2’s reduced expression could also increase healthspan by reducing cancer risk." (PMID 32559200, 2020). "Consistent with this, BRD2 knockdown sensitized cancer cells to BETi in vitro, and combining BRD2 depletion and JQ1 treatment significantly impaired tumor growth in vivo." (PMID 42069518, 2026). "Collectively, our findings establish BRD2 as a critical mediator of pan-cancer adaptive resistance to BETi and identify NFYA as a novel transcriptional regulator of this process." (PMID 42069518, 2026). "Small-molecule BETi targeting of the epigenetic reader BRD–containing proteins BRD2, BRD3, and BRD4 has been developed to cause cancer cell death." (PMID 40632844, 2025). "Folate-ARV-771 demonstrated efficient BRD2/3/4 protein degradations in cancer cells through a mechanism that is dependent on folate receptor alpha (FOLR1), but not in normal non-cancerous ones." (PMID 38389844, 2024). "On the other hand, among the four BET family of proteins, Brd4 has been the most extensively studied, whereas the relative role of Brd2/Brd3 in cancer cell survival still remain elusive." (PMID 37049806, 2023). "The BET family of proteins (Brd2, 3, 4, and T) are of significant clinical interest due to their role in cell cycle regulation, epigenetic sensing, and a range of cancers from oral, breast, prostate, lung, colon, to myeloid leukemia." (PMID 37049806, 2023). "In Brd2+/- mice, longevity is increased by 23% (p<0.0001), and, relative to wildtype animals (Brd2+/+), cancer incidence is reduced by 43% (p<0.001)." (PMID 32559200, 2020). "Second, the persuit of cancer-related clinical trials for BET inhibitors suggests that Brd2 haploinsufficiency reduces cancer incidence in humans, just as our HET mice showed markedly reduced cancer incidence compared to WT." (PMID 32559200, 2020). "Brd2 haploinsufficiency significantly reduces the incidence of cancer at necropsy and facilitates healthier aging." (PMID 32559200, 2020). "Our results showed that mRNA and protein expressions of BRD2 were found to be significantly higher in HCC tissues, and mRNA expression of BRD2 was remarkably linked with cancer stages and tumor grades." (PMID 32927435, 2020). "In cancer stem cells, several studies mentioned that targeting BRD2 and BRD4 inhibited GIC proliferation and BRD4‐depleted induced GIC apoptosis." (PMID 33135348, 2020). "Downregulation of CCNA2 in our study is consistent with the observation that overexpression of BRD2 upregulated the transcription of CCNA2 which led to aggressive cancer in the mouse." (PMID 26830473, 2016). "The object of this study were three of the four BET proteins BRD2, BRD3 and BRD4 and to our knowledge, this is the first spectroscopic characterization in solution of human BRDs variants found in cancer." (PMID 27403962, 2016).
cancer (continued). "Previous studies have reported that overexpression of BRD2 occurs in human cancers." (PMID 40652527, 2025). "AT1 significantly degraded BRD4 (DC50 = 10-100 nM, Dmax > 90%) in all tested cancer cells; however, it showed negligible activity against BRD2 and BRD3, suggesting that AT1 demonstrated a greater degree of selectivity in its ability to deplete BRD4 compared to MZ1." (PMID 38389844, 2024). "However, most previous studies of BETi mainly examined BRD2/BRD3/BRD4 proteins in cancer cells; few studies have considered the effects of BETi on macrophages." (PMID 35094142, 2022). "Bromodomain containing 2 (BRD2) plays key role in transcription of genes required for cancer." (PMID 34079823, 2021). "Furthermore, work from The Cancer Genome Atlas (TCGA) shows that BRD2 expression is elevated across 32 distinct tumor types and establishes BRD2 as a promising drug target for human cancers." (PMID 32559200, 2020). "Hence, the overexpression of BRD2 is oncogenic, whereas inhibiting the activity of BRD2 limits cancer progression." (PMID 32559200, 2020). "However, dual targeting of BRD2 and BRD4 have presented some limitations, recent studies revealed their opposing biological effects in some cancer types, which BRD2 inhibition increased cancer cell invasiveness." (PMID 31523195, 2019). "Although changes in expression of Brd2 have been linked to certain human cancers, the newly described bromodomain protein Brd2 also performs profound, diverse and non-redundant functions in adipogenesis, energy metabolism and inflammation." (PMID 24194944, 2013). "In addition, germline mutations associated with increased cancer risk have been reported in over 100 genes, and targeted sequencing has found variants in suspected familial or sporadic NPC susceptibility genes CDKN2A/2B, BRD2, TNRFRSF19, and CLPTM1L/TERT." (PMID 35954343, 2022). "We also replicated two variants in the transcription regulator gene BRD2, though this variant was not included in our primary variant-based case-control association test as BRD2 did not satisfy the criterion of being a known cancer gene in cancer gene databases or the literature sources." (PMID 35954343, 2022). "Thus, inhibiting the activity of BRD2 in humans may increase longevity (and/or healthier aging) by reducing cancer incidence." (PMID 32559200, 2020). "In summary, BRD2 expression is higher in LUAD tissues than in normal tissues and is positively correlated with different stages of cancers." (PMID 40652527, 2025). "BMS-986158, a highly selective and potent inhibitor of BRD2/BRD4, has demonstrated anti-cancer activity through the downregulation of BRD4 and c-MYC expressions in preclinical efficacy studies and a clinical trial for patients with solid tumors (NCT02419417)." (PMID 40937321, 2025). "We proceed with investigating the expression of BRD2 in data from CPTAC, a publicly available resource that provides protein expression and clinical information of thousands of cancer patients." (PMID 40652527, 2025). "The BET family is composed by BRD2, BRD3, BRD4, and BRDT, and plays important roles in cancer by directly regulating the expression of cancer-related genes such as MYC, and the transcription factor NF-κB." (PMID 41551874, 2025). "Bromodomain and outdomain (BET) proteins, mainly composed of BRD2, BRD3, and BRD4 proteins, function as epigenetic readers and transcription coactivators and are currently recognized as therapeutic cancer targets." (PMID 41049615, 2025). "BRD1, BRD2, BRD3, BRD4, and BRD7-9 were significantly upregulated in tumor samples expressing high levels of p16, a surrogate biomarker for HPV-positive cancers, and the presence of HPV DNA through in situ hybridization, compared to normal samples (p<0.05)." (PMID 39301555, 2024).